GARS1 (glycyl-tRNA synthetase 1)
Diseases named in the same sentence as GARS1 in open-access papers (continued):
Sharing a sentence is not in itself a finding about the gene and the disease.
cancer (continued). "Nonetheless, our analyses indicate that GARS1 represents a promising target for multiple cancer types, possibly owing to one or more of these functional roles." (PMID 38235113, 2023). "GARS1 holds promise as a potential prognostic marker and therapeutic target for pan-cancer immunotherapy, offering valuable insights for the development of more precise and personalized approaches to tumor treatment in the future." (PMID 37404826, 2023). "We investigated the correlation between GARS1 expression and immune subtypes in human cancers using the TISIDB website." (PMID 37404826, 2023). "Equally, altered protein levels of FLNA, HSPA7, HGF, ERO1A, and GARS1, have been related to cancer migration, adhesion, poor patient prognosis, and metastasis." (PMID 35008958, 2022). "Secreted GARS1 interacts with cadherin 6 (CDH6) on neighboring cancer cells, leading to phosphatase 2 A (PP2A) release, which deactivates the ERK signaling pathway." (PMID 35501376, 2022). "Higher GARS1 mRNA levels correspond to significantly worse survival in five different cancer types (BLCA, KIRC, LGG, LIHC, and LUAD) compared to only one for KARS1 (HNSC)." (PMID 33266490, 2020). "Studies have suggested that GARS1 modulates the cell cycle through its involvement in neddylation, raising the possibility that targeting GARS1 could inhibit cancer, as exemplified by small molecule neddylation inhibitors." (PMID 38235113, 2023). "Initially, we examined the expression levels of GARS1 across multiple cancer types." (PMID 37404826, 2023). "While this activity has yet to be definitively demonstrated in humans, the conservation of the localization signal in human GARS1 implies that mTOR activation through GARS1 could be an advantageous pathway exploited by cancer cells." (PMID 38235113, 2023). "The role of GARS1 in human cancer prognosis and immunology has been minimally explored to date." (PMID 37404826, 2023). "We analyzed the impact of GARS1 expression on patient prognosis in a pan-cancer cohort." (PMID 37404826, 2023). "Additionally, a substantial correlation exists between GARS1 expression and immune subtypes in the majority of cancers, indicating its involvement in immune regulatory processes." (PMID 37404826, 2023). "However, the role of GARS1 in human cancer prognosis and its impact on immunology remain largely unexplored." (PMID 37404826, 2023). "GARS1 expression varies among immune subtypes across different cancer types." (PMID 37404826, 2023). "Collectively, these findings indicate the widespread expression of GARS1 in diverse cancer tissues." (PMID 37404826, 2023). "The relationship between the alterations of these cellular processes and cancer formation mechanisms described for other ARSs indicates that Fraisinib’s anti-tumoral activity could depend on GARS1 targeting." (PMID 38235113, 2023). "Additionally, GARS1 is secreted via specific EVs and promotes cancer cell apoptosis." (PMID 37780856, 2023). "It is noteworthy that there exists a strong correlation between glycine consumption and the expression of the mitochondrial glycine biosynthesis pathway across various cancer cells, suggesting that GARS1’s involvement in cancer may also relate to glycine metabolism." (PMID 38235113, 2023). "In addition, the identification of GARS1 as the drug target and the analysis of pathways deregulated by Fraisinib open new perspectives in the search for additional therapeutic adjuvants for this severe cancer." (PMID 38235113, 2023). "M1 macrophages exert anti-tumor activity in cancer environment, and could be induced by miRNA-33- and miRNA-130-overexpressing EVs as well as by macrophage-derived EVs expressing human glycyl-tRNA synthetase-1 that trigger cancer cell death." (PMID 37476156, 2023). "Hence, GARS1 holds promise as a prognostic and therapeutic biomarker across various cancers." (PMID 37404826, 2023).
cancer (continued). "It is currently unknown which of these activities dominates in the context of cancer, or whether there is a pattern of tissue specificity among them, but our analyses suggest that GARS1 represents a promising target for several types of cancer, possibly due to one or more of these functionalities." (PMID 33266490, 2020). "It is noteworthy that CD276 was significantly positively correlated with GARS1 in 24 types of cancer, while CD274 (PD-1) was significantly positively correlated with GARS1 in 15 types of cancer." (PMID 37404826, 2023). "Data on six immune infiltrating cells from the TIMER database were downloaded for 32 cancer types (excluding LAML), and the correlation between GARS1 expression and immune cell scores was analyzed." (PMID 37404826, 2023). "For instance, in the case of LGG, GARS1 exhibited lower expression in the C1 and C2 modules but relatively higher expression in KIRP, indicating distinct roles in cancer progression." (PMID 37404826, 2023). "Specific aaRSs that are differentially upregulated across many cancer types include TARS1 (n = 23), DARS2 (n = 22), GARS1 (n = 21), YARS2 (n = 21), EPRS1 (n = 20), AIMP2 (n = 19), and FARSA (n = 18)." (PMID 33266490, 2020). "The findings indicated that, except for MESO and UVM due to the unavailability of adjacent normal tissue data, GARS1 expression was markedly higher in the majority of human cancers (29/33) when compared to adjacent non-cancerous tissues." (PMID 37404826, 2023). "Additionally, we investigated the relationship between GARS1 and ICP genes across different types of cancer." (PMID 37404826, 2023). "In our study, GARS1 expression exhibited a negative correlation with stromal and immune scores in the majority of tumors, implying predominant expression by cancer cells." (PMID 37404826, 2023). "Moreover, we identified a positive correlation between GARS1 expression and epithelial-mesenchymal transition (EMT) in various cancers, such as BLCA, GBM, LAML, MESO, PCPG, and SARC, suggesting a potential involvement of GARS1 in tumour invasion and migration." (PMID 37404826, 2023). "However, in cancers like BLCA and SARC, immune score and stromal score displayed significant positive correlations with GARS1 expression, signifying the presence of abundant immune cells during tumor progression." (PMID 37404826, 2023). "It was also found that macrophages cultured in glucose-depleted medium secreted human glycyl-tRNA synthetase 1 (GARS1)-EVs, which involved an immunological defense response against tumorigenesis and could promote cancer cell death." (PMID 34071980, 2021).
peripheral neuropathy (14 papers, 2016 to 2025). A disorder affecting the peripheral nervous system. "We next evaluated the effect of dGlyRS knock-down in motor neurons (OK371-GAL4), because motor neurons are the affected cell type in all GARS1-associated peripheral neuropathies." (PMID 40119731, 2025). "Dominant, missense mutations in the widely and constitutively expressed GARS1 gene cause peripheral neuropathy that usually begins in adolescence and principally impacts the upper limbs." (PMID 32848623, 2020). "Here, we refer to these GARS1-associated peripheral neuropathies as PN-GlyRS." (PMID 40119731, 2025). "In addition to CMT2D, heterozygous GARS1 mutations have been linked to related peripheral neuropathies characterized by selective motor axonal degeneration and lacking sensory involvement, including distal hereditary motor neuropathy type V (dHMN-V) and infantile spinal muscular atrophy (iSMA)." (PMID 40119731, 2025). "We previously identified a pathogenic gain-of-toxic function mechanism underlying peripheral neuropathy (PN) caused by heterozygous mutations in the GARS1 gene, encoding glycyl-tRNA synthetase (GlyRS)." (PMID 40119731, 2025). "Here, we addressed this question for peripheral neuropathy associated with mutations in GARS1, encoding GlyRS." (PMID 40119731, 2025). "Dominantly inherited, missense mutations in the widely expressed housekeeping gene, GARS1, cause Charcot-Marie-Tooth type 2D (CMT2D), a peripheral neuropathy characterised by muscle weakness and wasting in limb extremities." (PMID 32703932, 2020).
tumor (10 papers, 2014 to 2025). "GARS1 exhibited high expression in the “CD4Tconv” “Mono/Macro” and “CD8T” cell clusters across most tumors, suggesting a robust association between GARS1 and tumor immunity." (PMID 37404826, 2023). "In order to provide further guidance for tumor treatment, we investigated drugs that are closely associated with GARS1." (PMID 37404826, 2023). "Additionally, we examined the association between GARS1 expression and tumor MSI." (PMID 37404826, 2023). "Macrophage-derived EVs can also deliver glycyl-tRNA synthetase (GARS1), which suppresses tumor growth by promoting M1 polarization and enhancing phagocytosis." (PMID 41511353, 2025). "Features such as TMB, MSI, MMR, and neoantigens are strongly correlated with GARS1 in numerous tumor types." (PMID 37404826, 2023). "Our analysis of single-cell data revealed that GARS1 performs distinct functions depending on the tumor type." (PMID 37404826, 2023). "We then investigated the relationship between GARS1 expression and the tumor immune microenvironment by employing the ESTIMATE algorithm." (PMID 37404826, 2023). "At the single-cell level, we observed a strong correlation between GARS1 and the tumor immune microenvironment." (PMID 37404826, 2023). "Contrary to these previous findings, secreted GARS1 has also been observed to induce apoptosis in tumor cells by binding to K-cadherin on the cell surface and releasing phosphatase 2A (PP2A), resulting in ERK dephosphorylation and apoptosis." (PMID 38235113, 2023). "Our findings reveal a correlation between GARS1 and immune checkpoint genes across 33 tumor types, suggesting the influence of GARS1 on tumor immunotherapy." (PMID 37404826, 2023). "Second, we lack direct evidence elucidating the impact of GARS1 on tumor prognosis through its involvement in immune infiltration." (PMID 37404826, 2023). "This indicates that GARS1 can serve as an effective marker for predicting the efficacy of tumor immunotherapy." (PMID 37404826, 2023). "Conversely, in tumors like BLCA and SARC, a significant positive correlation existed between immune score, stromal score, and GARS1 expression, implying the presence of abundant immune cells during tumor progression." (PMID 37404826, 2023). "Additionally, our study revealed that GARS1 is linked to several immune-regulated signaling pathways, including MYC_TARGETS_V1, MYC_TARGETS_V2, and E2F_TARGETS, providing further evidence of the strong connection between GARS1 and tumor immunity." (PMID 37404826, 2023). "We propose a compound that successfully fights tumor growth in vivo by targeting the enzyme GARS1." (PMID 38235113, 2023). "Additionally, UMAP plots of cell clusters and corresponding GARS1 gene scatter plots were depicted for CRC_GSE146771 and SKCM_GSE72056, demonstrating the pronounced expression of GARS1 in immune microenvironment cell types within both tumor types." (PMID 37404826, 2023). "Moreover, it offers valuable insights into the involvement of GARS1 in tumor immunotherapy." (PMID 37404826, 2023). "The results revealed a significant positive correlation between GARS1 expression and MMR gene expression in the majority of tumors, indicating a potential synergistic effect of GARS1 in tumor repair processes." (PMID 37404826, 2023). "Specifically looking at the cytoplasmic aaRS members, the genes that are preferentially amplified across most tumor types are TARS1, GARS1, MARS1, AIMP2, and AIMP3/EEF1E1." (PMID 33266490, 2020). "Remarkably, specific aaRS genes do show a DNA profile reminiscent of an oncogene (e.g., GARS1, AIMP2, and YARS2) or tumor suppressor (e.g., NARS1, QARS1, LARS2, and RARS2)." (PMID 33266490, 2020). "Macrophage-derived EVs have also been shown to transfer GARS1, which suppresses tumor growth by inducing M1 polarization, promoting macrophage phagocytosis via activation of the RAF-MEK-ERK pathway, and triggering tumor cell death through interaction with CDH6." (PMID 40317075, 2025).
GARS1 also shares sentences with these, for which no sentence is quoted: hyperekplexia (15 papers); startle disease (10); neurological disorders (7); Charcot-Marie-Tooth disease type 2D (4); epilepsy (4); Anxiety (3); autism (3); mitochondrial disease (3); myositis (3); depression (2); infection (2); neuroblastoma (2); schizophrenia (2); temporal lobe epilepsy (2); alcohol-use disorders (1); anxiety disorder (1); atherosclerosis (1); autosomal dominant disease (1); Charcot-Marie-Tooth neuropathy (1); cognitive deficits (1); colon cancer (1); distal hereditary motor neuropathy type V (1); encephalomyelitis (1); endometrial cancer (1); glioma (1); glycine encephalopathy (1); gouty arthritis (1); hematopoietic system tumors (1); inflammatory myopathy (1); influenza (1).
A further 11 diseases each share a sentence with GARS1 in 1 paper.